EPHA2 (EPH receptor A2)
Diseases named in the same sentence as EPHA2 in open-access papers (continued):
Sharing a sentence is not in itself a finding about the gene and the disease.
hepatocellular carcinoma (47 papers, 2011 to 2026). A malignant tumor that arises from hepatocytes. "Erythropoietin-producing hepatocellular carcinoma A2 (EphA2), a member of the EPH family of receptor tyrosine kinases, is widely expressed in various cancers and plays a pivotal role in tumor development and progression." (PMID 40181964, 2025). "In this study, we developed a new antibody targeting erythropoietin-producing hepatocellular carcinoma A2 (EphA2), which is highly expressed in NSCLC, and established CAR-T/ natural killer (NK) immune cells to verify its potential for immune cell therapy." (PMID 40181964, 2025). "The conditioned medium of hepatocellular CAFs promoted VM formation and the expression of VM-related genes and proteins (MMP2 and EphA2) in hepatoma cell lines." (PMID 38459564, 2024). "Potential new targets such as erythropoietin-producing hepatocellular carcinoma A2 (EphA2), tissue factor (TF), and protein tyrosine kinase 7 (PTK7) are currently under study in clinical trials." (PMID 37998743, 2023). "Potential new targets such as erythropoietin-producing hepatocellular carcinoma A2 (EphA2), tissue factor (TF), and protein tyrosine kinase 7 (PTK7) are currently under investigation in clinical trials." (PMID 37998743, 2023). "These targets are erythropoietin-producing hepatocellular carcinoma A2 (EphA2), tissue factor (TF), and protein tyrosine kinase 7 (PTK7)." (PMID 37998743, 2023). "First identified as epithelial cell kinase (eck), ephrin type-A receptor 2 (EPHA2) belongs to the largest subfamily of receptor tyrosine kinases that were originally discovered in a human erythropoietin-producing-hepatoma (EPH) cell line." (PMID 34685586, 2021). "EphA2 overexpression was identified as required for overcoming sorafenib resistance in hepatocellular carcinoma cells: in fact, ligand mimicry in combination with sorafenib abated the resistance in vitro and in vivo by triggering EphA2 degradation." (PMID 33572284, 2021). "For instance, knockdown of miR-520d-3p promoted cell growth by inhibiting long non-coding RNA MIAT and EPHA2 expression in hepatocellular carcinoma." (PMID 34872448, 2021). "For instance, ligand-bound EphA2 attenuated Erk activation in primary keratinocytes and hepatoma cells; Ephrin-A/EphA signaling suppressed Erk activation induced by IGF-1 in myoblasts, facilitating myogenic differentiation." (PMID 33572284, 2021). "Erythropoietin-producing hepatocellular carcinoma A2 (EphA2) mediates tissue renewal and embryonic morphogenesis, but its dysregulation has been associated with tumorigenesis and metastasis in many cancers." (PMID 32182776, 2020). "The activation of the erythropoietin-producing hepatoma (EPH) receptor A2 (EphA2) is involved in FGF production." (PMID 32754598, 2020). "VE-cadherin induces erythropoietin-producing hepatocellular carcinoma-A2 (EphA2) to interact with its membrane bound ligand and become phosphorylated." (PMID 30915348, 2019). "The erythropoietin-producing hepatoma (EPH) receptor A2 (EphA2) belongs to the Eph family of receptor tyrosine kinases." (PMID 30451837, 2018). "HC-04 cells exhibited clear inter-cellular variations in levels of EphA2, similar to the findings reported from hepatoma Hepa1-6 cultures." (PMID 29370800, 2018). "The first member, named EphA1, was cloned from an erythropoietin-producing hepatocellular cancer cell line and the second member, EphA2, was identified by screening the human epithelial (Hela cells) cDNA library." (PMID 28752098, 2017). "EFNA1 was overexpressed in hepatocellular carcinoma and can inhibit growth of malignant mesothelioma by phosphorylating EPHA2." (PMID 23158542, 2012). "To address this question, we utilized an immortalized liver epithelial cell line, LK133A, isolated from a hepatoma induced by DEN in EphA2 knockout mice." (PMID 22916121, 2012).
hepatocellular carcinoma (continued). "Inhibiting the activity of a protein known as EphA2 may help overcome the development of drug resistance during treatment of hepatocellular carcinoma, the most common form of liver cancer." (PMID 32203105, 2020). "EPH-receptor A2 (EPHA2) is a member of the erythropoietin-producing hepatocellular-carcinoma (EPH) sub-family of receptor tyrosine kinases (RTKs) that play critical signaling roles in embryonic development, adult tissue homeostasis, and cancer development and progression." (PMID 29267365, 2017). "In addition, the level of Tyr-593-phosphorylated (activated) pro-apoptotic erythropoietin-producing human hepatocellular carcinoma receptor tyrosine kinase A2 (EphA2) increased after doxazosin treatment (50 μM) by 2.8±0.29-fold (n = 3; p = 0.048)." (PMID 24516604, 2014). "EphA1 was the first discovered Eph receptor tyrosine kinase and was cloned in 1987 from a hepatocellular carcinoma (HCC) cell line; next, in 1990 the screening of a cDNA library of HeLa cells brought the identification of EphA2." (PMID 36142306, 2022). "Clinical trial involving Ephrin type-A receptor 2 (EphA2) and M2 subunit of ribonucleotide reductase (R2) siRNA-mediated therapy are currently ongoing for Hepatocellular carcinoma (HCC)patients and solid tumors, respectively." (PMID 33322132, 2020). "Thus our findings regarding the targeting of EphA2 may provide an effective approach for overcoming sorafenib resistance and may contribute to the management of advanced hepatocellular carcinoma." (PMID 32203105, 2020). "The present evidence indicates that signaling by EPHA2 and its ligand, EFNA4, promotes hepatocellular carcinoma cell migration and the combination of EFNA4 and EPHA10 promotes proliferation and migration in oral squamous cell carcinoma cells." (PMID 36077763, 2022). "For instance, EFNA3/EPHA2 axis can promote cancer stemness in hypoxic hepatocellular carcinoma by modulating metabolic plasticity, and EFNA3 is served as a prognostic biomarker for hepatocellular cancer." (PMID 37768204, 2023).
lung cancer (44 papers, 2013 to 2025). A malignant neoplasm involving the lung. "EPHA2, a receptor tyrosine kinase, promotes the proliferation and migration of lung cancer cells and is associated with poor prognosis of lung cancer." (PMID 37351348, 2023). "In particular, EPHA2 is frequently expressed in nonsmall cell lung cancers (90%) and metastatic melanomas (67%) in association with poor prognostic outcomes." (PMID 31160603, 2019). "We have recently shown that EphA2 is overexpressed in lung cancer and harbors a gain-of-function point mutation in some squamous cell carcinomas, and EphA2 inhibition in addition to rapamycin exposure in lung cancer cells reduced their proliferation in vitro." (PMID 23844053, 2013). "This study showed that CAR-T/NK cells targeting EphA2 have anticancer effects against A549 and H460 lung cancer cell lines in vitro and in vivo." (PMID 40181964, 2025). "The findings of this study highlight the potential of CAR-T/NK cell therapy targeting EphA2 as an effective treatment for lung cancer, particularly NSCLC with high EphA2 expression." (PMID 40181964, 2025). "Recent studies have indicated that EphA2 enhances the radioresistance of lung cancer cells 14, 15, suggesting that EphA2 can serve as a radiosensitization target for tumor radiotherapy." (PMID 39897046, 2025). "In lung cancer, pegylated EphA2 peptide-coated nanoparticles simultaneously delivered two therapeutic agents with high affinity for lung tumor cells expressing EphA2." (PMID 39596256, 2024). "High levels of B7-H3, B7-H4, IDO1, and EphA2 expression in lung cancer are correlated to a poor prognosis." (PMID 38267913, 2024). "In breast as well as in lung cancer, it was shown that high phosphorylation levels of EPHA2 induced by RPS6KA1 enhance cellular migration and tissue invasion capacity." (PMID 37414921, 2023). "The N-terminus of CiP can specifically bind to the membrane of lung cancer cells, and the target paired with CiP is the erythropoietin hepatocellular carcinoma receptor A2 (EPHA2) on the surface of lung cancer cells." (PMID 38155903, 2023). "A VV encoding a secretory BiTE, named EphA2-TEA-VV, has been designed to target against EphA2 in lung cancer cells." (PMID 37041165, 2023). "It has been reported that inhibition of EphA2 by ALW-II-41-27 reverses TKI resistance in lung cancer cells." (PMID 37063424, 2023). "Particularly, together with T cells a VV encoding a secretory BiTA consisting of two scFvs specific for CD3 and EphA2 (EphA2-TEA-VV) had potent antitumor activity in comparison with control VVs plus T cells in a lung cancer xenograft model." (PMID 37491263, 2023). "For PTX-targeted delivery, YSAYPDSVPMMS (YSA) peptide was successfully tested to selectively target Ephrin type-A receptor 2 (EphA2) activation when anchored with liposomal docetaxel (a common clinical formulation of PTX) in A549 lung cancer cell line." (PMID 38131939, 2023). "The targeting moieties on these nanoparticles are Ephrin transmembrane receptors A2 (EphA2) that are highly expressed on the surfaces of lung cancer cells." (PMID 35893781, 2022). "Two mutations in EGFR, L858R and T790M, that are frequently observed in lung cancer patients, promoted binding to EphA2, and this binding was dependent on Ephexin1." (PMID 35668076, 2022). "For example, blockade of EphA2 has been shown to overcome acquired resistance to EGFR kinase inhibitors in lung cancer." (PMID 36230684, 2022). "EphA2, highly expressed on lung cancer cells, plays a major role in cancer recurrence and metastasis and often results in poor prognosis and survival of NSCLC patients." (PMID 35893781, 2022).
lung cancer (continued). "These NPs were loaded with radiosensitizer NU7441 and chemotherapeutic drug Cisplatin for enhanced chemo-radiotherapy of lung cancer and functionalized with EphA2 antibodies to impart lung cancer cell targeting functionalities to the NPs." (PMID 35893781, 2022). "Our findings showed that the modification of YSA peptide improved the cytotoxicity of YSA‐PEG‐TiOX/CTD to EphA2 overexpressing A549 non‐small cell lung cancer (NSCLC) than non‐YSA modified counterparts." (PMID 32246815, 2020). "The therapeutic potential of EphA2 is evident from its elevated expression in lung cancer cells that are resistant to EGFR tyrosine kinase inhibitor (TKI) and decreased viability of these resistant cells by pharmacological inhibition of EphA2." (PMID 29682554, 2018). "Consistent with a previous study in lung carcinoma, the present results support EphA2 expression as an important index of disease progression." (PMID 25013485, 2014). "For example, ephrin-B3 knockdown revealed that this ephrin increases EphA2 expression in the U-1810 lung cancer cell line." (PMID 24348920, 2013). "We indeed found that ephrin-A3 overexpressed in lung cancer cells can inhibit EphA2 and EphA3 activation by ephrins in trans while overexpression of ephrin-B2 can inhibit activation of EphA3 and EphB4." (PMID 24348920, 2013). "However, overexpression of EphA2 is observed in several solid cancers, such as prostate, ovarian, breast, cervical, colorectal, and lung cancers, including RCC." (PMID 41440001, 2025). "In addition, EphA2 was found overexpressed in diverse cancers, among which lung cancer, also reported in our findings, was provided with a pointed strategy targeting EPHA2 blockade." (PMID 37449541, 2023). "Furthermore, the incorporation of EphA2 provided targeting of the NPs to the lung cancer cells, while sparing the healthy cells, thus reducing the chances of off-target drug toxicity." (PMID 35893781, 2022). "EphA2 blockade was reported to overcome resistance to EGFR kinase inhibitors in lung cancer." (PMID 32814829, 2020). "Subsequent in vivo studies in a lung cancer xenograft model expressing the tumor antigen EphA2 revealed that EphA2-TEA-VV, when applied in combination with adoptively transferred human T cells, mediated superior antitumor activity when compared with control VV plus T cells." (PMID 32664210, 2020). "Previous study shows that Epha2 blockade could overcome acquired resistance to EGFR kinase inhibitors in Lung Cancer." (PMID 30615629, 2019). "CARTs targeting fibroblast activation protein-α (FAP), a tumor stromal-associated antigen expressed by CAFs, delivered in combination with an EphA2-targeting CAR population was shown to control the tumor growth in an A549 lung cancer model more effectively than either agent alone." (PMID 30386740, 2018). "Furthermore, EPHA2 protein expression in brain metastases was significantly higher compared to matched primary lung cancers (n = 10)." (PMID 25025847, 2014). "In addition, EphA2 was recently shown to demonstrate a similar trend in lung cancer in which patients expressing low levels of EphA2 had a median survival that was over threefold longer than in patients with strong EphA2 expression." (PMID 23844053, 2013). "Thus, in lung cancer cells, coexpressed ephrin-A3 can inhibit EphA2 and EphA3 activation by ephrin ligands." (PMID 24348920, 2013). "Additionally, the molecular mechanisms by which tumor-specific EphA2 alters the chemokine milieu and immune landscape of lung cancer may be very complex." (PMID 40867322, 2025). "In an analysis of survival rates among lung cancer patients, the higher the expression of Ephexin1, EGFR, EphA1, and EphA2, the lower the rate." (PMID 35668076, 2022). "The activity prediction algorithm was then implemented for the regulatory networks of six important lung cancer oncogenes (FAK, PXN, MET, RON (MST1R), EPHA2, AXL)." (PMID 29731983, 2018).
lung cancer (continued). "On the other hand, phosphorylation of EPHA2 promotes SRC activation and is involved in the acquisition of resistance of lung cancer cells to EGFR-TKIs." (PMID 29050315, 2017). "Similarly, the pharmacologic inhibition of EPHA2 by the small molecule inhibitor ALW-II-41-27 reduced the viability of resistant tumor cells and inhibited tumor growth in vivo in lung cancer models." (PMID 34691070, 2021). "Moreover, Ser-897-phosphorylated EphA2 co-localizes with phosphorylated active form of RSK in various human tumour specimens, and this double positivity is related to poor survival in lung cancer patients, especially those with a smoking history." (PMID 26158630, 2015). "Thus, our results suggest that CAR-T/NK cells targeting EphA2 may be an efficient immune cell therapy for lung cancer, particularly NSCLC, with increased EphA2 expression." (PMID 40181964, 2025). "Likewise, in H1299 lung cancer cells, there was no increase in binding of EphA2 to the EGFR mutant when Ephexin1 was absent." (PMID 35668076, 2022). "Co-activation of MET, AXL, ERBB2, and EPHA2, and co-activation of DDR1 with EGFR, DDR2, HCK, PDGFRA, and FGR is evidence that simultaneous activation of multiple tyrosine kinases may be common in lung cancer." (PMID 23300999, 2013).
cataract (26 papers, 2008 to 2024). Partial or complete opacity of the crystalline lens of one or both eyes that decreases visual acuity and eventually results in blindness. "Of three missense variants located within the TK domain of EPHA2 (amino acid residues 613–871), two (p.G668D, p.Q669H) have been associated with early-onset cataract and one (p.R721Q) with age-related cortical cataract in humans." (PMID 34685586, 2021). "In this study, we identified functional variants of EPHA2 in two unrelated families with bilateral mild microphthalmia and cataracts, and demonstrated a significant reduction in eye size of epha2a/b morphant zebrafish at 3 dpf." (PMID 33671840, 2021). "This demonstrates that age as a function of genotype has a significant effect on Epha2-related cataract development, which correlates with association of variants in the human EPHA2 gene with the risk of developing age-related cataract." (PMID 34495288, 2021). "The loss of EPHRIN-A5, a disputed ligand of EPHA2 in the lens, also leads to age-related cataract in mice." (PMID 34495288, 2021). "Our work and other recent studies show that loss of EphA2 or ephrin-A5 in the lens can causes cataracts and abnormal cell membranes, cytoskeletal networks, and fiber cell morphologies." (PMID 34899394, 2021). "Multiple mutations in the EPHA2 gene have been recently shown to cause cataracts in humans, contributing to the destabilization of the receptor and the loss of cell migration activity." (PMID 27681698, 2016). "Early analyses linked the EPHA2 gene with autosomal dominant cataract and several recent studies have attempted to determine the association between EPHA2 and age-related cataract." (PMID 23976972, 2013). "Comprising 1071 cortical cataract cases, 2600 nuclear cataract cases, 4776 any cataract cases, and 3616 controls, these three studies assessed more than eight SNPs in the EPHA2 gene for their associations with age-related cataract." (PMID 23976972, 2013). "Genetic analyses have shown that the 1p36 locus encodes mutated EPHA2 in human populations with cataracts." (PMID 24705208, 2013). "This notion is strongly supported by the observations both EPHA2 mutations in humans and EphA2 inactivation in mice also result in cataracts." (PMID 24705208, 2013). "Of particular interest has been the finding that four of the total known seven cataract mutations in EPHA2 are located within the SAM domain, suggesting that this domain plays a critical role in the regulation of EPHA2 function and lens development." (PMID 24705208, 2013). "We aimed to confirm the association of these three 3′ EPHA2 SNPs with age-related cataracts in the Indian population." (PMID 22412971, 2012). "Recent studies have shown that mutations or deletion of EphA2 gene lead to cataracts in humans and mice." (PMID 22570727, 2012). "Complementing these observations, our previous study identified that the loss of ephrin-A5 also leads to cataracts in mice, indicating that EphA2 serves as a receptor for the ligand in maintaining the clarity of the crystalline lens." (PMID 22570727, 2012). "Our previous studies showed that ephrin-A5 acts as a ligand for EphA2 in the lens, and the loss of ephrin-A5 function leads to cataracts in mice." (PMID 22570727, 2012). "Our study suggests that both SNP rs477558 and SNP rs7548209 of EPHA2 are associated with age-related cortical cataract in a Han Chinese population." (PMID 21686326, 2011). "Recent studies report that ephrin-A5 knockout (-/-) mice develop cataracts with variable severity and incomplete penetrance, and EphA2 mutations lead to age-dependent cortical cataracts in humans and mice." (PMID 22140528, 2011). "Here, we report for the first time a missense mutation in EPHA2 associated with autosomal recessive congenital cataracts." (PMID 20361013, 2010).